SREBF1 (sterol regulatory element binding transcription factor 1)
Diseases named in the same sentence as SREBF1 in open-access papers (continued):
Sharing a sentence is not in itself a finding about the gene and the disease.
Hyperinsulinemia (74 papers, 2011 to 2026). An increased concentration of insulin in the blood. "The reduction of hyperinsulinemia and associated hepatic SREBF1 activity observed herein, indicate that hepatic insulin signaling may be improved with 2′-FL, supported by the significant reduction of hepatic DAG." (PMID 35782914, 2022). "On the other hand, hyperinsulinemia and hyperglycaemia promote triglyceride synthesis by activating carbohydrate-responsive element-binding protein sterol regulatory element-binding transcription factor 1 (SREBF1c)." (PMID 35013433, 2022). "The relationship between hyperinsulinemia NAFLD and atherosclerosis has been explained by an insulin‐mediated upregulation of SREBF1 (SREBP‐1c)." (PMID 35830259, 2022). "HFD-induced hyperinsulinemia in BALB/c, C57BL/6J and 129S6 mice may explain Srebf1 upregulated transcription." (PMID 24324835, 2013). "The differentially expressed Srebf1 and Insig2 between CON, WD and FOH groups suggest that high fat feeding induced de novo lipogenesis mainly attributed to highly Srebf1 expression in rats but not hyperinsulinemia induced SREBP1c mature, and the process was rescued by fish oil feeding." (PMID 26832365, 2016). "Furthermore, differences were observed in genes contributing to fatty acid, cholesterol and triglyceride metabolism (FATP2, ELOVL6, PNPLA3, SREBF1) and in genes involved in regulating lipolysis (ANGPTL4) between the insulin-resistant and -sensitive subjects especially during hyperinsulinemia." (PMID 22471940, 2012).
prostate carcinoma (71 papers, 2009 to 2025). A carcinoma that arises from epithelial cells of the prostate gland. "Our findings highlighted a close association between SREBF1 and ferroptosis resistance in prostate cancer." (PMID 39988626, 2025). "We confirmed the association between SREBF1-mediated metabolic reprogramming in prostate cancer and ferroptosis in human samples, using a combination of single-cell sequencing and Bulk-RNA analysis." (PMID 39988626, 2025). "We constructed a risk score based on SREBF1 target genes associated with the biochemical recurrence of prostate cancer by combining bulk RNA analysis." (PMID 39988626, 2025). "In conclusion, our study revealed the role of SREBF1-mediated metabolic reprogramming in prostate cancer and its association with ferroptosis resistance." (PMID 39988626, 2025). "Subsequently, we used the SREBF1 target gene to construct a risk score for the biochemical recurrence (BCR) of prostate cancer." (PMID 39988626, 2025). "A biochemical recurrence risk scoring model based on the SREBF1 target gene identified several genes closely related to the biochemical recurrence of prostate cancer and demonstrated a good predictive effect." (PMID 39988626, 2025). "SREBF1 target genes are associated with biochemical recurrence of prostate cancer." (PMID 39988626, 2025). "This indicates that SREBF1 is crucial for the metabolic reprogramming of prostate cancer, and that its mediated metabolic changes promoted ferroptosis resistance in prostate cancer in multiple ways." (PMID 39988626, 2025). "In this study, we investigated the relationship between metabolic reprogramming and ferroptosis in prostate cancer regulated by SREBF1." (PMID 39988626, 2025). "In fact, Klf5 co-regulation of Srebf1 in the control of lipid biogenesis has been found in squamous and prostate cancer." (PMID 40250760, 2025). "By combining single-cell sequencing and Bulk-RNA analysis, we demonstrated that the metabolic changes regulated by SREBF1 promote ferroptosis resistance in prostate cancer." (PMID 39988626, 2025). "We observed characteristic differences in fatty acid and cholesterol metabolism between normal prostate tissue and prostate cancer tissue, identifying high transcriptional activity of SREBF1 in prostate cancer tissue." (PMID 39988626, 2025). "SREBF1 significantly influences metabolic reprogramming in prostate cancer cells, leading to ferroptosis resistance." (PMID 39988626, 2025). "Considering the regulation of metabolic reprogramming in prostate cancer by SREBF1 and its relationship with ferroptosis, we investigated the effect of the SREBF1 inhibitor Betulin on promoting ferroptosis in prostate cancer." (PMID 39988626, 2025). "Nuclear SREBF1 and H2A-K130ac levels are significantly increased and directly correlated with late-stage prostate cancer, reversal of which sensitizes castration-resistant prostate cancer (CRPC) to androgen synthesis inhibitor, Abiraterone." (PMID 37296155, 2023). "SREBF1 was involved in fatty acid metabolism, and expression of SREBF1 mediated by AR/mTOR complex accelerated metabolism of fatty acid, to meet the demand for prostate cancer cell growth." (PMID 34116604, 2021). "In prostate cancer cells, miR-185 and miR-342, was described to target SREBF1 and FASN inducing apoptosis." (PMID 33050166, 2020). "SREBF1 gene has been shown as up-regulated in the prostate cancer and the early growth response 1 (EGR-1) is a transcription factor regulates the expression of its dependent genes involved in cell growth or survival." (PMID 20025723, 2009). "In summary, we have identified androgen related gene TMPRSS2 that is regulated by SREBF1, PBX1 and ETS family members that are associated with the prostate cancer and gene TMPRSS2 has been found in 80% of tumor experiments." (PMID 20025723, 2009).
prostate carcinoma (continued). "Moreover, we found that SREBF1 inhibitors have excellent chemosensitizing effects in prostate cancer therapy, highlighting their potential for therapeutic applications in prostate cancer." (PMID 39988626, 2025). "In vivo experiments verified the excellent therapeutic effect of Betulin and its chemosensitizing effect on docetaxel, suggesting that SREBF1 inhibitors may have a promising therapeutic potential in prostate cancer." (PMID 39988626, 2025). "Finally, we investigated the effect of the SREBF1 inhibitor Betulin on promoting ferroptosis in prostate cancer." (PMID 39988626, 2025). "Prostate cancer samples were divided into two groups based on the expression level of SREBF1." (PMID 39988626, 2025). "Additionally, we validated SREBF1 as a potential therapeutic vulnerability and an effective target for prostate cancer by employing SREBF1 inhibitors." (PMID 39988626, 2025). "Furthermore, SREBF-1 expression is significantly elevated in advanced prostate cancer tissues, showing its potential involvement in tumor progression and emerging therapy resistance." (PMID 39168364, 2024). "AR signaling also impacts the cellular metabolism reprogramming observed in prostate cancer via binding, together with mTOR, to regulatory regions of the sterol regulatory element-binding transcription factor 1 (SREBF1) gene, which leads to increased expression." (PMID 36768610, 2023). "Further, it indicates that H2A-K130ac marks may have a direct impact on nuclear SREBF1 expression in stage IV prostate cancer." (PMID 37296155, 2023). "Activation of FXR by CDCA inhibits proliferation of prostate cancer cells, reduces lipid anabolism via inhibiting Sterol Regulatory Element Binding Transcription Factor 1 (SREBF1) and induces the expression of the tumor suppressor phosphatase and tensin homolog (PTEN)." (PMID 35429253, 2022). "Importantly, our results demonstrated that SREBF1 inhibitors can significantly enhance the therapeutic effect and chemosensitization of prostate cancer, suggesting a promising therapeutic potential for the treatment of prostate cancer." (PMID 39988626, 2025). "Previous research has shown that the SREBF1 inhibitor Betulin can significantly increase ROS levels and decrease GSH levels in prostate cancer cells." (PMID 39988626, 2025). "GATA3 regulation happened in the early stage and the outcome of the prostate cancer at the late stage of tumor development that are related to genes MZF1, SREBF1, PRL, and DDIT3." (PMID 20025723, 2009). "Finally, our experiments verified that SREBF1 inhibitors can significantly promote an increase in ROS, the decrease in GSH, and the decrease in mitochondrial membrane potential in prostate cancer cells and confirmed their chemosensitization effect in vivo." (PMID 39988626, 2025). "Intriguingly, SREBF1 has been report to interact with the epigenetic marks in cancer development, recruiting KAT2A/GCN5 to deposit the epigenetic mark H2A-K130ac on SREBF1, thereby reigniting lipogenesis and steroidogenesis in prostate cancer." (PMID 39962068, 2025). "Finally, it has been described in prostate cancer that genetic alterations of ACACA, FASN, and SREBF1 predicted worse overall patient survival." (PMID 33194695, 2020). "Follow-up studies confirmed the increased epoxycholesterol levels, including products of the LXR target gene SREBF1 during prostate cancer disease progression and direct implication of LXR in PCa based on inhibited proliferation of prostate cancer cell lines by LXR agonists." (PMID 29286311, 2017).
hyperlipidemia (63 papers, 2010 to 2026). "A study explored the association of SREBF1 rs9902941 polymorphisms and response to various statins among 386 Chinese patients with hyperlipidemia." (PMID 37818163, 2023). "However, the activation of LXR promoted the transcription of liver lipid synthesis related genes like SREBF1, FASN, SCD, and ACACA, leading to liver steatosis and hyperlipidemia." (PMID 39645039, 2024).
type 2 diabetes (63 papers, 2009 to 2026). "These directional associations, coupled with previous work implicating SREBF1 in type 2 diabetes risk via adiponectin and the plausible relevance of ADIPOQ as the gene encoding adiponectin, reinforce these CpGs as promising epigenetic markers." (PMID 41057690, 2026). "Coupled with evidence that SREBF1 expression decreases type 2 diabetes risk by increasing serum adiponectin and the clear relevance of ADIPOQ to adiponectin production, there is now considerable support for their direct regulatory potential in metabolic risk." (PMID 41057690, 2026). "Results from the majority of those studies indicate that differentially methylated sites in the TXNIP, ABCG1, CPT1A and SREBF1 genes are associated with type 2 diabetes and glycaemic traits." (PMID 29164275, 2018). "One SNP (rs2297508) within SREBF1 gene has been reported across a few populations to be associated with the risk of type 2 diabetes." (PMID 25270430, 2014). "Considering the collective evidence at the ADIPOQ and SREBF1 loci, and since the SREBF1 CpG has also previously been associated with HbA1c and incident type 2 diabetes, we investigated the broader implications of these sites for metabolic disease using bidirectional 2SMR." (PMID 41057690, 2026). "Methylation of the SREBF1 CpG (cg11851174) plausibly decreased HDL-cholesterol levels (pfdr=4.11 × 10−3) and increased both fasting insulin (pfdr=3.84 × 10−3) and risk of type 2 diabetes (pfdr=2.39 × 10−5)." (PMID 41057690, 2026). "Genes annotated to CpGs that were associated with type 2 diabetes included ABCA1, ABCG1, CPT1A, SREBF1, SLC7A11, SLC7A5, and TXNIP among others (see S12 Table for full details)." (PMID 37410739, 2023). "The replicated associations for type 2 diabetes implicated genes including ABCG1, CPT1A, SREBF1, and TXNIP." (PMID 37410739, 2023). "A nested case-control study including 25,372 individuals identified five loci that were associated with future type 2 diabetes incidence, including ABCG1, PHOSPHO1, SOCS3, SREBF1, and TXNIP." (PMID 35399937, 2022). "In both studies, increased methylation in the ABCG1 and SREBF1 genes and decreased methylation in the TXNIP gene at baseline were associated with incident type 2 diabetes." (PMID 35169870, 2022). "The results from our meta-analysis included CpG sites at genes that are known to be associated with type 2 diabetes, such as TXNIP, ABCG1, SREBF1 and CPT1A, showing consistency between cross-sectional and longitudinal studies and also between ethnicities." (PMID 35169870, 2022). "Methylation of CpG6, which is centred in the SREBF1 E-box motif, was significantly decreased in the liver of individuals with type 2 diabetes (−4.92%; p = 0.0152; pa = 0.0029)." (PMID 32710190, 2020). "In this study, we replicated five CpGs in blood, from which four reside in the genes previously shown to be associated with type 2 diabetes (ABCG1, LOXL2, SLC1A5, SREBF1)." (PMID 29164275, 2018). "It has been recently shown that methylation changes of the CpGs located in SREBF1, ABCG1 and CPTA1 were not only associated with type 2 diabetes but also with BMI." (PMID 29164275, 2018). "The authors estimated that 32% of the unexplained risk for future type 2 diabetes among Indian Asians compared with controls was associated with a higher methylation score based on the top five markers at TXNIP, ABCG1, SREBF1, SOCS3 and PHOSPHO1." (PMID 29164275, 2018). "An EWAS of BMI reported differential methylation at CPT1A and ABCG1, and an EWAS of type 2 diabetes at SREBF1 and ABCG1." (PMID 27350042, 2016). "A meta-analysis of genome wide scans in European populations showed linkage with type 2 diabetes in the 17p11 region, which comprises the SREBF1 gene." (PMID 25270430, 2014). "A meta-analysis of four European genome screens found the strongest linkage with type 2 diabetes on chromosome 17p11.2-q22 where is located the SREBF1 gene." (PMID 25270430, 2014).
type 2 diabetes (continued). "A large-scale gene-centric meta-analysis identified the SREBF1 gene as a type 2 diabetes loci among Europeans, with rs4925115 being the most significantly associated SNP." (PMID 25270430, 2014). "The association of ABCG1, SREBF1, and TXNIP with the incidence of type 2 diabetes could be reaffirmed in an independent replication study, thus rendering these factors promising for clinical use as biomarkers." (PMID 35159278, 2022). "Additionally, CpG6, which is located in intron 1 of IRS2, was hypomethylated in type 2 diabetes; this site spans the sterol regulatory element binding transcription factor 1 (SREBF1) recognition motif, which likely acts as transcriptional repressor." (PMID 32710190, 2020). "In our Lifelines sample, five out of 52 included CpGs showed significant associations with type 2 diabetes (the Bonferroni-adjusted p < 0.0009 (0.05/52 CpGs)), including the loci in the ABCG1, LOXL2, TXNIP, SLC1A5 and SREBF1 genes (see a short description in ESM Box 1)." (PMID 29164275, 2018). "In our study, methylation within the SREBF1 E-box motif was significantly decreased in individuals with type 2 diabetes, as compared with those without, despite receiving glucose-lowering medication." (PMID 32710190, 2020). "Furthermore, a prospective study in Finland on non-diabetic population showed DNA methylation of SREBF1 and ABCG1 genes were associated with HbA1C, glucose levels and type II diabetes risk." (PMID 35655232, 2022). "Similarly, a methylation score based on five markers located in ABCG1, PHOSPHO1, SOCS3, SREBF1, and TXNIP could predict future type 2 diabetes incidence independent of established risk factors." (PMID 35159278, 2022). "Recent epigenome-wide association studies (EWASs) in blood have identified differentially methylated CpG sites (DMS), in individuals with vs without type 2 diabetes, in genes such as TXNIP, ABCG1 and SREBF1." (PMID 35169870, 2022).
lipid metabolism disorders (55 papers, 2017 to 2026). "Overall, our findings showed HFD might influence the process of β-oxidation of fatty acid (Ppara, Acox, and Pgc1a), lipolysis (Atgl, Srebf1, and Hsl), cholesterol removal (Lxra), and appetite regulation (Leptin), leading to lipid metabolism disorder." (PMID 35967777, 2022).
Hyperglycemia (54 papers, 2012 to 2025). An increased concentration of glucose in the blood. "Together with SREBF1, these transcription factors activate the downstream lipogenic genes and thus could explain the association of NAFLD with T2D or hyperglycemia." (PMID 35052690, 2021). "Thus, whilst male and female IVF offspring both display hyperglycemia, this may be due to alternative activation of Ppargc1α or Srebf1 pathway." (PMID 25405530, 2014). "Furthermore, hyperglycemic cultures had elevated FASN and SREBF1 gene expression, whereas the expression of MLXIPL was unchanged by hyperglycemia as compared to normoglycemic cultures." (PMID 27312339, 2016).
non-alcoholic fatty liver disease (43 papers, 2011 to 2025). "For example, microbes with differential abundance in non-alcoholic fatty liver disease (NAFLD) are significantly enriched for SREBF1 and LPL genes via literature-based associations." (PMID 33293650, 2020). "Hence, the roles of those overlapping microbes associated with SREBF1 and LPL that also exhibit abnormal abundance in non-alcoholic fatty liver disease merit further investigations." (PMID 33293650, 2020).
hypertriglyceridemia (41 papers, 2010 to 2025). A laboratory test result indicating elevated triglyceride concentration in the blood. "Activation of transcription factor LXRa increased SREBF1 expression, leading to hepatic lipogenesis and hypertriglyceridemia." (PMID 35154608, 2021). "Thus, decreasing the expression of SREBF1 might be the reason of hypertriglyceridemia." (PMID 35551677, 2022).
glioblastoma (40 papers, 2013 to 2025). The most malignant astrocytic tumor (WHO grade IV). "The overexpression of SREBF1 is related to a variety of cancers such as PCa, breast, head and neck, colorectal, endometrial, glioblastoma, pancreatic, and ovarian." (PMID 28651018, 2017).